INS (insulin)
Diseases named in the same sentence as INS in open-access papers (continued):
Sharing a sentence is not in itself a finding about the gene and the disease.
Abdominal obesity (continued). "These were all obese, with abdominal obesity, abnormalities in lipid profile, blood glucose >6.0 mmol/L, insulin and FFA levels in the upper quartile of the calculated range for the studied population." (PMID 20622341, 2010). "Relevant defects of platelet function in central obesity are related also to a reduced sensitivity to mediators—such as insulin, prostacyclin (PGI2), and NO—which in lean subjects reduce platelet sensitivity to proaggregating stimuli." (PMID 20652043, 2010). "A 12-week aerobic training program decreased insulin resistance and abdominal obesity, and chemerin concentrations in overweight and obese subjects." (PMID 22375203, 2010). "In our sample, there were more subjects below the 75th percentile of the HOMA-IR or insulin distribution, who had abdominal obesity, elevated blood pressure, low HDL-C levels, elevated TC/HDL-C ratio or elevated triglycerides." (PMID 18088443, 2007). "PC3 (stocky central obese type): Combines high BMI and central obesity, accounting for 34.1% of high-stable TyG individuals (vs. 6.9% in low-stable group); monitor insulin resistance (e.g., TyG index, fasting insulin) as it correlates with significantly higher digestive system cancer risk." (PMID 41064293, 2025). "Consequently, acute coughing in patients with abdominal obesity and INS resistance is more likely to progress to PIC." (PMID 40708638, 2025). "Central obesity is also an important driver of insulin resistance and proinflammatory signaling." (PMID 38152892, 2024). "Physical inactivity leads to abdominal obesity by reducing energy expenditure, metabolism, and insulin sensitivity while disrupting hormonal balance, promoting muscle loss, and increasing the risk of metabolic and cardiovascular diseases linked to abdominal fat accumulation." (PMID 39494070, 2024). "However, hormonal changes that occur during the menstrual cycle, pregnancy and menopause can cause fluctuations in insulin response, which can increase the risk of IFG and central obesity." (PMID 38917085, 2024). "Furthermore, egg white hydrolysate was able to augment insulin sensitivity and mitigate abdominal obesity." (PMID 38398871, 2024). "Sympathetic activation is elevated in obese humans, especially in those with abdominal obesity, due to insulin's stimulatory influence, which may be a factor in MetS development in obese people." (PMID 37248529, 2023). "Reduced expression of TFAP2B may have a protective effect against diminished insulin sensitivity and central obesity-related complications such as T2DM and coronary artery disease." (PMID 36627697, 2023). "Accordingly, mild suppression of hyper-FGF21 without unfavorable insulin-associated metabolic changes should be an interesting strategy to prevent or treat OVX/menopause-caused central obesity." (PMID 37834368, 2023). "In people with normal-weight central obesity, regular exercise, even with little or no weight loss, can bring about a variety of beneficial changes, such as improved glucose homeostasis and insulin sensitivity." (PMID 37810923, 2023). "Instead, the risk for glioma of abdominal obesity was more pronounced in non-insulin users than in insulin users." (PMID 36928679, 2023). "A diet with high DII and DIL may increase central obesity by reducing insulin sensitivity, which may, in turn, decrease lipolysis, resulting in augmented fat storage and therefore an increased risk of MetS." (PMID 37226148, 2023). "On the other note, mice with BCHE gene deficiency developed central obesity and an impaired lipid profile, as well as early signs of the T2D phenotype characterized by marginally elevated FBG and significantly elevated fasting insulin levels." (PMID 35055468, 2022). "Central obesity and ectopic intraabdominal fat accumulation might also contribute to the sex differences in glucose and insulin metabolism." (PMID 35246259, 2022).
Abdominal obesity (continued). "However, in another study with adolescents, WC explained a greater variance in abdominal obesity and insulin sensitivity than BMI percentile did." (PMID 36079745, 2022). "The current reduction in abdominal obesity after the three training programs may be a key to the improvement in insulin resistance." (PMID 36554057, 2022). "As such, visceral fat may be a key element in the pathogenesis of NAFLD in PWH independently of insulin resistance and classical anthropometric measures of abdominal obesity." (PMID 36359434, 2022). "More attempts to lose weight may lead to weight fluctuation, subsequent increase in abdominal obesity and insulin resistance." (PMID 35022546, 2022). "Second, we did not measure hormones or laboratory indexes (e.g., ghrelin, leptin, insulin resistance, or sympathoadrenal activity), which might be the mediator between sleep quality and central obesity." (PMID 34348705, 2021). "In addition, four out of seven RCT studies revealed significant effects of Vit D on BP, abdominal obesity, and insulin and glucose metabolism, which are the three core components of MetS." (PMID 34589329, 2021). "The absence of association with waist circumference and percentage of body fat, also indicates that the body fat distribution is not consistent with insulin-resistance state, as revealed by the null association with markers of central obesity." (PMID 33909378, 2021). "Furthermore, animal experiments suggest that central obesity and fatty liver induced by a high-fat diet are prevented when a decrease in insulin clearance is inhibited." (PMID 34572340, 2021). "In addition to abdominal obesity, high levels of fasting insulin are present, by which the organism tries to overcome the biological effect of insulin reduction." (PMID 33494341, 2021). "However, conclusions regarding the nature of the influence of physical activity and abdominal obesity on insulin sensitivity vary." (PMID 33376604, 2020). "Dietary interventions designed to increase insulin sensitivity through the consumption of complex carbohydrates and unsaturated fatty acids were reported to reduce abdominal obesity through mechanisms such as reduction of adipose tissue mass and absorption of fat in the body." (PMID 32938011, 2020). "However, the ORs for insulin-requiring GDM were higher in current smokers with general obesity (2.19 [1.64–2.93]) or abdominal obesity (2.14 [1.60–2.86]) compared with other groups." (PMID 32807828, 2020). "The results of previous studies showed that only central obesity and visceral obesity were associated with impaired carbohydrate metabolism, as shown by the higher insulin and glucose levels in obese women than in nonobese women." (PMID 32571278, 2020). "In fact, the reduction in total body fat, abdominal obesity or both, without significant weight loss (more than 5%) showed improvements in the cardio-metabolic risk factors, such as insulin sensitivity." (PMID 33467351, 2019). "It is of importance that some individuals with normal BMI are insulin resistant and have metabolic abnormalities, which might contribute to an abnormal fat distribution, especially abdominal obesity." (PMID 31730482, 2019). "One possible interpretation of our findings on differences between people with abdominal and non-abdominal obesity is that insulin levels may influence brain function during rest in brain networks that control reward and food regulation." (PMID 30364290, 2018). "The main effect of central obesity was observed in insulin, PAI-1, chemerin and IL-6." (PMID 30114249, 2018). "However, results also indicated that abdominal obesity plays a much bigger role in insulin resistance than fiber intake, although both are significant contributors." (PMID 29461482, 2018).
Abdominal obesity (continued). "Another objective was to ascertain the extent to which potential mediating variables, including age, gender, race, smoking, body mass index (BMI), body fat percentage, abdominal obesity, and physical activity, influence the relationship between fiber intake and insulin resistance." (PMID 29461482, 2018). "The glucoregulatory functions of insulin have been widely studied, whereas the association of glucagon with abdominal obesity has been sparsely researched, and no study is available in South Asians." (PMID 28634585, 2017). "Thus the findings from this report and others reinforce the importance of reducing abdominal obesity for improving the management of insulin sensitivity in older adults." (PMID 27936206, 2016). "Physical activity may increase insulin sensitivity, glucose disposal, and oxidation of free fatty acids, which may reduce the complications of central obesity." (PMID 27467819, 2016). "We have found that during the OFLT, glucose and insulin values significantly decreased in abdominal obesity and control groups with a higher decrease in abdominal obesity subjects (50% at 6 h and 60% at 8 h in the abdominal obesity group)." (PMID 27537847, 2016). "Obese individuals, especially those with abdominal obesity, often have increased levels of insulin and insulin-like growth factor-1 (IGF-1), which may promote the development of SIC, as has been hypothesized for other gastrointestinal tumors." (PMID 27294726, 2016). "The interaction of PI’s catalytic site with LRP leads to a decrease in the cleavage of triglycerides into fatty acids and glycerol, a decrease in the hepatic uptake of chylomicron induced by central obesity, deposition of fat in the breasts and an increase in the peripheral resistance to insulin." (PMID 27740592, 2016). "Decreased levels of central obesity may affect insulin metabolism by decreasing the release of free fatty acids." (PMID 27340824, 2016). "In accordance with those data, the results from multiple regression analysis in our study have shown that impairments in daily fluctuation of PAI-1 were significantly and independently influenced only by WHR, as a marker of abdominal obesity, and AUC of insulin." (PMID 26089884, 2015). "Transplantation also diminished insulin requirements and decreased central obesity and fat mass." (PMID 25810037, 2015). "Furthermore, 29% of these individuals had low HDL-C, 21% had abdominal obesity and 63% were resistant to insulin, indicating a high percentage of young individuals with high probability of future worsening in cardiometabolic risks." (PMID 26702345, 2015). "It is believed that upper body and central obesity may expose the liver to higher free fatty acid concentrations, reducing liver clearance of insulin." (PMID 26196519, 2015). "Additional factors such as reduced secretion of adiponectin by adipose tissue may also contribute to the insulin-resistant state in individuals with abdominal obesity." (PMID 24744783, 2014). "It has been suggested that higher BMD with MS is largely determined by abdominal obesity, and protective effects of fat mass may promote bone formation via high mechanical loading, high circulating insulin levels, and factors that are co-secreted with insulin." (PMID 25492884, 2014). "Associations between NWO with HOMA2-IR and insulin sensitivity were not totally explained by central obesity because after further adjustment for WC, these associations nearly halved although continued to be significant." (PMID 23556000, 2013). "They attributed low levels of ghrelin in obese patients to the effects of insulin, whereas in our study, after adjustment for insulin effects as a confounding factor the inverse relationship between acylated ghrelin with overall and abdominal obesity remained significant." (PMID 24354802, 2013). "Animal studies have suggested that exposure to POPs may induce abdominal obesity, impair insulin sensitivity, and reduce glucose uptake." (PMID 23131992, 2013).
Abdominal obesity (continued). "Minor A allele carriers of rs4766587 had increased MetS risk (OR 1.29) compared with the GG homozygotes, which may in part be explained by their increased BMI, abdominal obesity, and impaired insulin sensitivity." (PMID 23306188, 2013). "Therefore, the present study compared the efficacy and safety of adding liraglutide versus increasing insulin dose strategy in insulin-treated poorly controlled T2D and abdominal obesity." (PMID 23153177, 2012). "While an increase in total body mass was associated with a moderate decline in peripheral sensitivity to insulin, abdominal obesity was characterised by a steep decline in such sensitivity and was accompanied by a reduction in glucose peripheral stimulus and a reduction in insulin output." (PMID 21776204, 2011). "Thus the metabolic features of PCOS involve a complex interplay between increased androgen concentrations, insulin signaling, central obesity and NAFLD." (PMID 21935484, 2011). "The low sensitivity of waist circumference for identifying insulin resistant young black men and women suggests that central obesity may need to be combined with other abnormalities to improve the ability to identify those with this condition." (PMID 21134291, 2010). "Indeed, these results confirm those of previous studies that found improvement in insulin sensitivity after aerobic training and abdominal obesity reduction in obese individuals." (PMID 22375203, 2010). "While an increase in total body mass was associated with a moderate decline in peripheral sensitivity to insulin, abdominal obesity was characterized by a steep decline in such sensitivity accompanied by a reduction in glucose peripheral stimulus and a reduction in insulin output." (PMID 21318152, 2010). "The central obesity and lower appendicular muscle mass may have negative health consequences (i.e., insulin resistance, inflammation, high fall risk) in the absence of any meaningful differences in BMI." (PMID 39125296, 2024). "Additionally, the effects of E2 on insulin sensitivity may be mediated at least partly by E2‐induced inhibition of abdominal obesity." (PMID 35238495, 2022). "Thus, visceral fat, which retains most of its mitochondrial function despite NRTI treatment, may expand in the presence of an inflammatory environment and impaired insulin-stimulated glucose uptake resulting in central obesity." (PMID 35246167, 2022). "The evidence based on clinical and experimental studies demonstrates that C-peptide could stimulate glucose transport, dampen the metabolic effects of insulin at high serum concentrations, promote lipids accumulation in adipocytes and vascular walls, and accelerate central obesity." (PMID 35996181, 2022). "Furthermore, we asked whether T-EMRA cells and changes in Trp metabolites are potential mediators between abdominal obesity and disturbed insulin sensitivity." (PMID 33922813, 2021). "In addition, the treatment of healthy people who are moderately overweight with GW501516 results in a significant reduction in fasting plasma insulin, and the dual PPARα/δ agonist GFT505 (elafibranor) improves hepatic and peripheral insulin sensitivity in men with abdominal obesity." (PMID 32708786, 2020). "Nevertheless, the relationship was strong among US adults with abdominal obesity (4th quartile), suggesting that high levels of physical activity may play a meaningful role in glucose and insulin metabolism in those with abdominal obesity (4th quartile), but not in adults with smaller waists." (PMID 33376604, 2020). "This suggests that high plasma Cys (or central obesity) could also play a role in insulin sensitivity and related disorders in these subjects, where the relationship between plasma fasting glucose and Cys levels was very significant as well (r = 0.29; P < 0.001)." (PMID 31321096, 2019).
Abdominal obesity (continued). "In another study, the authors applied the same techniques on cross-sectional data from 4700 adults aged 20–90 years, and reported that reducing abdominal obesity might play an important role in the pathway through which Mediterranean diet consumption reduces insulin resistance and inflammation." (PMID 30223829, 2018). "In that study, however, no attempt was made to determine whether the association between changes in abdominal obesity and insulin sensitivity remained independent of corresponding changes in CRF." (PMID 27936206, 2016). "Furthermore, examination of associations between C3 polymorphisms and MetS risk demonstrated that common genetic variants at the C3 locus were associated with risk of the MetS and its phenotypes including dyslipidaemia, abdominal obesity and insulin sensitivity." (PMID 23306188, 2013). "Moreover, the association between IR and central obesity but not BMI suggested the effect of body fat distribution on insulin metabolism." (PMID 22287962, 2012). "For instance, partial replacement of meat with plant protein has been shown to improve insulin sensitivity and total and LDL cholesterol levels in postmenopausal women with abdominal obesity." (PMID 39011855, 2024). "Reduced expression of PAH was found in pigs with MetS, TH expression was found lower in individuals with central obesity, and lowered expression of TAT in the liver was reported in insulin-resistant mice." (PMID 37328862, 2023). "The aim of this study was to examine the association of abdominal obesity assessed by dual-BIA with basal and post-load β-cell function, and clarify whether VAT and subcutaneous adipose tissue (SAT) have the same predictive effect on insulin secretion and sensitivity in Chinese patients with T2DM." (PMID 36909323, 2023). "We also wanted to see how increased fructose consumption affected plasma basal insulin and GLP-1 levels, as well as glucose, insulin resistance, lipid profiles, and abdominal obesity." (PMID 37886000, 2023). "Participants with central obesity had a higher BMI, waist circumference, hip circumference, waist‐to‐hip ratio, body fat percentage, circulating glucose, TAG, insulin, HOMA‐IR, and DBP than participants who were lean (ES ≥ 0.71)." (PMID 38011590, 2023). "Increased muscle insulin sensitivity, lipoprotein lipase activity in active musculoskeletal, transport of lipids and lipoproteins from the peripheral blood circulation and tissues to the liver, and reduction abdominal obesity are mechanisms by which MetS may improve with fitness." (PMID 33849567, 2021). "A similar trend was found for abdominal obesity, total cholesterol, TG/HDL ratio, insulin levels, and HOMA-IR with hsCRP levels." (PMID 34277535, 2021). "In the populations with central obesity and elevated BP, TRE improved body weight and fat, fasting glucose levels obtained by CGM, insulin resistance, and oxidative stress." (PMID 33466692, 2021). "TRT improves glycemic control, insulin sensitivity, and lipid parameters in hypogonadism patients with T2DM and MetS, partially through reducing central obesity." (PMID 33061966, 2020). "Administration of 200 μg/day Se supplements for 6 weeks resulted in a significant decrease in serum insulin and HOMA-IR levels among women with central obesity and PCOS." (PMID 28380029, 2017). "That reduction in abdominal adiposity mediates the association between exercise and insulin sensitivity independent of total adiposity is consistent with a large body of cross-sectional evidence confirming a strong independent association between abdominal obesity and insulin sensitivity." (PMID 27936206, 2016). "Vaspin (visceral adipose tissue-derived serpin) was firstly found in an abdominal obesity with T2DM animal model and was shown as a new adipocytokine to influence insulin sensitivity of white adipose tissues in obese rats." (PMID 27409634, 2016).